HMGB1 (high mobility group box 1)
Diseases named in the same sentence as HMGB1 in open-access papers (continued):
Sharing a sentence is not in itself a finding about the gene and the disease.
Hyperbilirubinemia (1 paper, 2014). An increased amount of bilirubin in the blood. "As an effective inflammatory mediator of TNF-α or endotoxin (LPS), HMGB1 may progressively exacerbate the inflammation and damage of the bile duct, intrahepatic cholestasis, and hyperbilirubinemia during the early stages of ACLF." (PMID 25187820, 2014).
hypertrichosis (1 paper, 2019). Excessive hair growth anywhere on the body. "Because it is released upon injury, HMGB1 may have a role in post-traumatic or post-inflammatory hypertrichosis." (PMID 31040377, 2019). "Thus, HMGB1 signalling may explain the paradoxical hypertrichosis that occurs following laser epilation and hypertrichosis in other inflammatory or traumatic circumstances." (PMID 31040377, 2019).
idiopathic interstitial pneumonia (1 paper, 2022). A class of diffuse lung diseases that typically affect the pulmonary interstitium, although some also have a component affecting the airways (for instance, Cryptogenic organizing pneumonitis). "HMGB-1 was reported to predict the development of acute exacerbation (AE) appearing pathologically as diffuse alveolar damage, and ALI/ARDS and mortality after AE onset, in idiopathic interstitial pneumonia patients." (PMID 35204430, 2022).
idiopathic thrombocytopenia (1 paper, 2024). "However, in patients with idiopathic thrombocytopenia, HMGB1 expression leads to a decrease in the Treg number." (PMID 38999957, 2024).
immune deficiency (1 paper, 2021). "There were significantly lower serum vitamin D receptor levels and significantly higher HMGB1 protein serum levels in the HIV group with severe immune deficiency (SID-HIV) than the HIV group with mild immune deficiency (MID-HIV) and the healthy control (HC) group." (PMID 33664952, 2021). "Increased HMGB1 was associated with a higher rate of inflammatory conditions in HIV patients and was further associated with immune deficiency conditions." (PMID 33664952, 2021). "This study aimed to examine differences and correlation of vitamin D receptor and HMGB1 protein levels in HIV patients with mild and severe immunodeficiency and healthy control participants." (PMID 33664952, 2021). "Strong negative correlation between VDR and HMGB1 in different immunodeficiency statuses suggesting an important role of vitamin D in inflammation control in HIV infection." (PMID 33664952, 2021).
Incisional hernia (1 paper, 2023). An abdominal hernia that occurs at a site of weakness in the abdominal wall resulting from an incompletely-healed surgical wound. "Therefore, TGF-β1:HMGB1 ratio determines the role of HMGB1 in incisional hernia tissues." (PMID 37296427, 2023).
inner ear diseases (1 paper, 2023). "In recent years, the role of HMGB1 in inner ear diseases has also been studied." (PMID 37998605, 2023).
Interstitial pneumonitis (1 paper, 2021). "Together our results reveal the potential ability of gefitinib to initiate sterile inflammation via two distinct mechanisms, and identified IL-1β and HMGB1 as key determinants of gefitinib-induced inflammation that may provide insights into gefitinib-induced interstitial pneumonitis." (PMID 33414419, 2021).
intervertebral disc degeneration (1 paper, 2024). "Furthermore, magnoflorine has been reported to attenuate M1 polarization-induced intervertebral disc degeneration by reducing HMGB1 expression and deactivating the MyD88/NF-kB pathway." (PMID 38493291, 2024).
intestinal infection (1 paper, 2018). "It has been shown that the HMGB1 level is a marker of intestinal inflammation associated with intestinal infection while there is no proven correlation between HMGB1 concentration and CD activity rates." (PMID 29991970, 2018).
intestinal schistosomiasis (1 paper, 2018). An intestinal infection that is caused by Schistosoma japonicum. "Intestinal schistosomiasis is another well-defined form of chronic schistosomiasis but its relationship with HMGB1 activity was not addressed in this paper." (PMID 30258438, 2018).
intestinal tumor (1 paper, 2025). "We next investigated whether HMGB1 was involved in GSDMC‐mediated intestinal tumor progression." (PMID 40213993, 2025).
intrahepatic cholestasis (1 paper, 2014). A cholestasis characterized by impairment of the bile flow caused by obstruction located in the liver. "The proliferation of large amounts of newly formed cholangioles accompanied by the release of the proinflammatory mediator HMGB1 suggests the possibility of intrahepatic cholestasis caused by inflammation around the cholangioles and bile duct." (PMID 25187820, 2014). "In the present study, it was investigated whether HMGB1 is released from cholangiocytes to induce cholangiole inflammation and the exacerbation of intrahepatic cholestasis in ACLF and if such a release can be induced by lipopolysaccharide (LPS) or tumor necrosis factor-α (TNF-α) in vitro." (PMID 25187820, 2014).
Intraventricular hemorrhage (1 paper, 2021). Bleeding into the ventricles of the brain. "In addition, compared with that of preterm infants without intraventricular hemorrhage (IVH), the concentration of HMGB1 in the umbilical cord blood of premature infants with IVH was significantly increased, suggesting that the increased HMGB1 levels may be related to IVH in preterm infants." (PMID 33140586, 2021).
joint disease (1 paper, 2020). "However, HMGB1 can also be released from activated immune cells present in inflamed tissues; this may explain the association between HMGB1 levels in serum and the presence of extra-muscular autoimmune manifestations, such as RP, joint disease and ILD." (PMID 32363191, 2020).
Kaposi's sarcoma (1 paper, 2023). A malignant neoplasm characterized by a vascular proliferation which usually contains blunt endothelial cells. "Despite its known role in promoting tumor growth and immune evasion in the tumor microenvironment, the contribution of HMGB1 to the development of Kaposi’s sarcoma (KS) is not well understood." (PMID 37520371, 2023).
latent infection (1 paper, 2023). "In KSHV-infected HMGB1 KO cells, we did not observe any alteration in the viral gene expression of KSHV compared to that in KSHV-infected WT cells, indicating that both WT and HMGB1 KO cells showed latent infection in KSHV-infected cells." (PMID 37520371, 2023).
Legionnaires' disease (1 paper, 2010). A pneumonia caused by Legionella pneumophila and other Legionella species, which is characterized by fever, cough, progressive respiratory distress, and which is often accompanied by extrapulmonary manifestations. "Because severe cases of Legionnaires' disease can occur against which antibiotic therapy alone is insufficient even using antibiotics with high antibacterial activities, this excessive inflammation involving HMGB-1 induced by L. pneumophila is associated with the severity of the pathogenesis." (PMID 21092200, 2010).
lentivirus infection (1 paper, 2020). Virus diseases caused by the Lentivirus genus. "RNA interference and lentivirus infection experiments were performed to investigate the involvement of HMGB1 in EMT process." (PMID 32117622, 2020).
leukopenia (1 paper, 2025). "Building upon the multilayer module network constructed, we identified key targets of CB herbs in the treatment of leukopenia, including TGFB1, C1R, CD4, and HMGB1, which regulate leukopenia through signal transduction, cellular process, and immune response." (PMID 40890790, 2025).
Limb tremor (1 paper, 2018). "PD patients with the mixed subtype mainly had the clinical manifestations of limb tremor and muscle rigidity, with serum HMGB1 and TLR4 levels of 5.12 ± 1.07 and 2.43 ± 0.87, respectively." (PMID 29670828, 2018).
lipid metabolism disorders (1 paper, 2022). "Some findings indicated that HMGB1 in hepatocytes prevents lipid metabolism disorders by maintaining β-oxidation and preventing endoplasmic reticulum (ER) stress, which suggests that stabilizing HMGB1 in liver cells may become an effective way to prevent and treat NAFLD." (PMID 36267567, 2022).
medulloblastoma (1 paper, 2017). A malignant, invasive embryonal neoplasm arising from the cerebellum. "Further, we also showed that SPARC altered cisplatin sensitivity by modulating the Let-7f-1 miRNA/ HMGB1 axis in medulloblastoma cells." (PMID 28435518, 2017).
monocytic leukaemia (1 paper, 2017). "The DAMPs calreticulin and HMGB1 were expressed on cell surfaces of the human monocytic leukaemia cell line THP-1, after co-culturing with ABAs." (PMID 29181774, 2017).
morbid obesity (1 paper, 2016). An excess of body weight, normally defined as an individual with a body mass index greater than 35 or a body weight greater than one hundred percent of ideal body weight. "Therefore, TLR8 expression changes need to be further investigated with regard to putative agonists like cellular RNAs and alarmins (e.g. HMGB1) which are known to be released during lipolysis in morbid obesity." (PMID 27980459, 2016).
muscle atrophy (1 paper, 2022). The loss of muscle tissue due to inactivity or disease. "Our in vivo work also shows that targeting HMGB1/IL-18 signaling rescues muscle-specific differentiation marker expression in glycerol-induced muscle injury, which indicates that targeting IL-18 is worthwhile for the treatment of skeletal muscle atrophy." (PMID 36497194, 2022).
muscular disease (1 paper, 2023). Myopathy is a peripheral nervous system disease consisting of any abnormal condition or disease of the muscular tissues; commonly designates a disorder involving skeletal muscle. "High mobility group box-1 (HMGB1) is a driver of inflammation in various muscular diseases." (PMID 37963838, 2023).
myelosuppression (1 paper, 2021). Myelosuppression or bone marrow suppression is a condition in which bone marrow activity is decreased, resulting in fewer red blood cells, white blood cells, and platelets. "Collectively, our data demonstrated that AS and SRP alleviated CTX-induced cell injury in BMHSCs via up-regulation of HMGB1 through inhibition of miR-142-3p, improved the hematopoietic function, and cured myelosuppression in CTX-induced myelosuppression mice." (PMID 33959499, 2021).
myonecrosis (1 paper, 2020). "In IMNM, this likely reflects rapid, passive release of HMGB1 into the extracellular space due to myonecrosis." (PMID 32363191, 2020). "In addition to cytokine and chemokine properties, HMGB1 can activate the classical pathway of complement, where complement deposition is a key mediator of myonecrosis." (PMID 32363191, 2020).
narcolepsy (1 paper, 2020). A sleep disorder characterized by a tendency for excessive sleepiness during the day which occurs even after adequate sleep in the nighttime. "Important genes and pathways that link PD, narcolepsy, and IR areCACNA1C, CAMK1D, BHLHE41, HMGB1, and AGE-RAGE." (PMID 34745571, 2020).
necrotizing fasciitis (1 paper, 2014). "HMGB1 expression increased in parallel to disease severity and was significantly higher in necrotizing fasciitis than in erysipelas (p = 0.0023)." (PMID 24524027, 2014). "However, little is known about local HMGB1 responses in acute necrotic bacterial soft tissue infections (STIs), such as necrotizing fasciitis." (PMID 24524027, 2014).
nematode infections (1 paper, 2022). "The results reported a significant level of HMGB-1 in the dogs with nematode infections, attributable to their central immune response." (PMID 36139753, 2022). "An increase in HMGB-1 has been reported in different nematode infections in humans and sheep." (PMID 36139753, 2022).
neurofibromatosis type 1 (1 paper, 2022). A clinically heterogeneous, neurocutaneous genetic disorder characterized by cafe-au-lait spots, iris Lisch nodules, axillary and inguinal freckling, and multiple neurofibromas. "Genes co-expressed with PTPN13 were correlated with “Immune response_HMGB1 release from the cell”, “Putative pathways of hormone action in neurofibromatosis type 1”, and “Immune response_HMGB1/RAGE signaling pathway”." (PMID 36556168, 2022).
occupational lung disease (1 paper, 2019). "Therefore, HMGB1-RAGE signaling is an attractive target to treat OD-induced occupational lung diseases." (PMID 30728013, 2019).
Opportunistic infection (1 paper, 2012). An infection that is caused by a pathogen that would generally not be able to cause an infection in a host with a normal immune system. "The formation of HMGB1/TLR ligand complexes has direct implications on immune activation, particularly in late stage of disease, where cell destruction and necrosis are dominant phenomena due to CD4+ T-cell loss, opportunistic infections, and other pathological conditions." (PMID 22719767, 2012).
oral lichen planus (1 paper, 2023). Oral lichen planus is a chronic inflammatory oral condition of unknown aetiology characterized by T-cell-mediated chronic immune response and abnormal epithelial keratinization cycle. "A research study investigating different HMGB1 genetic polymorphisms in OSCC and oral lichen planus patients, has shed light on OSCC risk, progression, and prognosis." (PMID 37511951, 2023).
oropharyngeal squamous cell carcinoma (1 paper, 2018). "In another study, by Qian investigated HMGB1 protein expression and clinicopathologic characteristics, as well as their association with overall survival time in oropharyngeal squamous cell carcinoma patients." (PMID 30245980, 2018).
osteonecrosis (1 paper, 2024). A none disease characterized by death of bone tissue due to a lack of blood supply. "Osteonecrosis (ON) is caused by a disruption of blood supply to the bone, resulting in ischemic cell death and the release of damage-associated molecular patterns (DAMPs), such as high-mobility group box 1 (HMGB1), s100, and inflammatory cytokines." (PMID 39056808, 2024).
Ovarian cyst (1 paper, 2023). The presence of one or more cysts of the ovary. "Healthy controls showed the lowest median age, the lowest median HMGB1 concentration and, together with the group of ovarian cysts, the highest median sRAGE concentration." (PMID 37894448, 2023).
ovary cystadenocarcinoma (1 paper, 2021). "Supporting this hypothesis, we found a positive correlation between increased HMGB1 gene expression and increased expression of genes involved in these processes, both in ovary cystadenocarcinoma and prostate adenocarcinoma tumours." (PMID 34572914, 2021).
papilloma (1 paper, 2015). A benign epithelial neoplasm that projects above the surrounding epithelial surface and consists of villous or arborescent outgrowths of fibrovascular stroma. "Leukocytic TLR-5 signalling mediates upregulation of the alarmin HMGB1 (High Mobility Group Box 1) in wound-induced papillomas." (PMID 25575023, 2015).
paraplegia (1 paper, 2025). Complete paralysis of the lower half of the body including both legs, often caused by damage to the spinal cord. "Our 11 min ischemia model represents a reproducible and physiologically relevant platform for studying delayed paraplegia following SCI/R injury and offers a suitable preclinical framework for assessing the efficacy of anti-HMGB1 mAb administration as a therapeutic intervention." (PMID 40943562, 2025).
parasites (1 paper, 2017). "Both ANA1 and mouse PMΦs released HMGB1 after parasites infection, and no obvious HMGB1 aggregation in cytoplasm compare to the IFN-γ treatment group." (PMID 28484433, 2017).
peritonsillar abscess (1 paper, 2025). An abscess that develops in the space surrounding one or both palatine tonsils. "In the univariate analysis, each 1 ng/mL increase in HMGB1 was linked to a 9% higher odds of peritonsillar abscess." (PMID 41153226, 2025).
pheochromocytoma (1 paper, 2025). "It is of note that seminoma and pheochromocytoma, the tumors with—by far—the highest rate of cases with HMGB1 deficiency, are derived from HMGB1-negative cell types." (PMID 40804938, 2025).
pituitary adenoma (1 paper, 2026). "The Escherichia coli are phagocytosed by the microglial cells in the pituitary gland, then activate GSDMD protein releasing HMGB1, and promote the tumorigenesis of pituitary adenoma by activating the MAPK pathway." (PMID 41655211, 2026).
Pleuritis (1 paper, 2022). Inflammation of the pleura. "In a model of S. aureus-induced lung injury in mice, the inhibition of high-mobility group box 1 (HMGB1), a RAGE ligand, by antibodies presented a reduction in lung edema, while Rage−/− mice showed a reduced pleuritis." (PMID 36235741, 2022).
pneumococcal pneumonia (1 paper, 2018). A febrile disease caused by STREPTOCOCCUS PNEUMONIAE. "However, high sputum HMGB1 level was associated with bacteraemia in pneumococcal pneumonia, indicating a potential role for HMGB1 in bacterial dissemination." (PMID 30194360, 2018).
pneumonitis (1 paper, 2018). An inflammatory process affecting the lung parenchyma. "HMGB1 was also higher in patients with other ALI, such as drug-induced pneumonitis and acute interstitial pneumonia." (PMID 29795561, 2018).
Pneumovirus Infections (1 paper, 2021). Infections with viruses of the genus PNEUMOVIRUS, family PARAMYXOVIRIDAE. "The RAGE-dependent upregulation of neurite outgrowth following prior in vivo pneumovirus infection suggests a role for HMGB1 in respiratory viral induced upregulation of neurite outgrowth." (PMID 34621188, 2021).
polyp (1 paper, 2023). A usually exophytic mass attached to the underlying tissue by a broad base or a thin stalk. "The use of polyp cancer lesions to explore this question offers the unique opportunity to assess HMGB1 expression in normal, adenomatous and malignant epithelium within the same lesion, eliminating inter-patient confounding." (PMID 36980751, 2023).
Prediabetes (1 paper, 2016). "In conclusion, we found plasma CTRP-3 levels were lower whereas plasma HMGB-1 concentrations were higher in subjects with prediabetes and newly diagnosed T2DM." (PMID 27738641, 2016). "Circulating CTRP-3 and HMGB-1 concentrations might be promising biomarkers to predict prediabetes and T2DM." (PMID 27738641, 2016).
pterygium (1 paper, 2015). A wedge-shaped fibrovascular lesion arising from the bulbar conjunctiva and extending to the cornea. "Considering that UV-induced chronic inflammation causes ocular surface change as pterygium, we have confirmed high HMGB1 translocation and ROS expression in human pterygium." (PMID 26313914, 2015). "Taken together, these data present that ROS production caused by UV induces chronic inflammation through HMGB1 translocation in the pterygial tissue and UV-induced ROS is involved in the HMGB1-mediated pterygium formation." (PMID 26313914, 2015). "To observe whether UV-induced HMGB1 secretion is associated with the inflammation that occurs during pterygium development, we first observed whether UV radiation could induce the nucleo-cytoplasmic translocation of HMGB1 in human conjunctival Chang cells." (PMID 26313914, 2015). "As a model disease, pterygium, the UV-induced chronic ocular surface inflammation, we found increased HMGB1 and ROS compared to the control samples." (PMID 26313914, 2015). "To measure the extracellular secretion of HMGB1, we collected the media from cultured pterygium and control tissues after 8 h of ELISA." (PMID 26313914, 2015). "Pretreatment of HMGB1 neutralizing proteins or ROS scavengers could block the chemotaxis of inflammatory cells suggesting that HMGB1 might be a possible therapeutic target for the treatment of UV-induced pterygium formation." (PMID 26313914, 2015). "HMGB1 levels in the culture supernatant were increased in pterygium tissues." (PMID 26313914, 2015). "In addition, it would be worthwhile to study the oxidative conditions of secreted HMGB1 SH residues in pterygium samples because only the fully reduced form of HMGB1, in which all three cysteines are in a thiol state, can function as a chemoattractant." (PMID 26313914, 2015).